CTSB (cathepsin B)
Diseases named in the same sentence as CTSB in open-access papers (continued):
Sharing a sentence is not in itself a finding about the gene and the disease.
glioma (continued). "On the other hand, cathepsin B overexpression reversed the inhibitory effects of ar-turmerone on glioma cell proliferation, mobility progression in vitro and in vivo." (PMID 37768200, 2023). "We then conducted bioinformatic Gene Expression Profiling Interactive Analysis using data from The Cancer Genome Atlas and Genome-Tissue Expression databases, and found that CTSB expression was elevated in glioma tissues." (PMID 37768200, 2023). "Shimizu demonstrated that an important process in the mechanism of Netrin-1–induced glioma angiogenesis and increased glioma invasiveness is cathepsin B–dependent." (PMID 37398678, 2023). "Subcutaneous tumorigenesis experiments revealed that CTSB overexpression disinhibited glioma cell tumor growth in ar-turmerone-treated mice, leading to greater tumor weights." (PMID 37768200, 2023). "Simultaneous RNAi-mediated targeting of MMP-9 and cathepsin B has potential application in the treatment of human gliomas." (PMID 36980765, 2023). "Degradation of tenascin-C around new blood vessels by CTSB can promote the expansion of new blood vessels, leading to glioma progression." (PMID 37576397, 2023). "Wound healing and Transwell assays respectively indicated that the inhibitory effects of ar-turmerone on glioma cell migration and invasion were alleviated upon CTSB overexpression." (PMID 37768200, 2023). "In glioma cells, knockdown of CTSB and uPAR reduced tumor growth and increased p27 nuclear expression in vivo." (PMID 37576397, 2023). "Cathepsin-B is overexpressed in various cancers such as breast, colorectal, gastric, lung, prostate cancer and gliomas." (PMID 37055381, 2023). "Silencing transient receptor potential mucolipin 1 (TRPML1) induces nitric oxide production, defective autophagy, and cathepsin B-dependent apoptosis in glioma cells." (PMID 37398678, 2023). "In brief, this research mainly focused on the expression pattern, biological function and clinical significance of CTSB in gliomas." (PMID 35277559, 2022). "We found that CTSB was significantly highly-expressed in HGG especially in WHO grade IV gliomas (P < 0.0001)." (PMID 35277559, 2022). "CTSB can increases the resistance of glioma cells to apoptosis and ferroptosis via lysosome-nuclear pathway of communication." (PMID 35277559, 2022). "To explore the expression pattern of CTSB in gliomas, we analyzed the RNA-seq data of glioma samples from TCGA and CGGA databases." (PMID 35277559, 2022). "Firstly, we drew Kaplan Meier curve with the survival data of glioma samples in the two databases, we found that patients with higher expression of CTSB would have shorter OS time (P < 0.0001)." (PMID 35277559, 2022). "Previous researches have demonstrated the meaning of CTSB for the progress of several tumors, whereas few clues about its immunological characteristic in gliomas." (PMID 35277559, 2022). "In gliomas, CTSB can bind to ANXA2 and induce the expression of vascular endothelial growth factor C, TGF-β, and MMP9 to promote angiogenesis." (PMID 36076905, 2022). "Cathepsin B is overexpressed during glioma cell migration and its expression correlates with the glioma grade." (PMID 35053605, 2022). "Then we performed receiver operator characteristic curve (ROC) to evaluate the specificity and sensitivity of CTSB in predicting mesenchymal subtype gliomas." (PMID 35277559, 2022). "Then we found that most of these genes are positively related to the expression of CTSB in both databases, which further reveals the role that CTSB plays in glioma-related immune activities." (PMID 35277559, 2022). "Other enzymes involved in glioma invasion are cysteine proteinases and serine proteases, such as cathepsin B and uPA." (PMID 35448036, 2022). "In this study, we aimed to comprehensively explore the expression pattern, biological functions and prognostic value of CTSB for gliomas, especially focusing on its role in glioma-related immune responses and immune cells infiltration." (PMID 35277559, 2022).
glioma (continued). "In glioma cell cultures, silencing of uPAR and cathepsin B downregulates the expression of CD133, Nestin, Sox2 and Bmi1 and reduces the number of glioma-initiating cells." (PMID 35493073, 2022). "CTSB-related biological processes in gliomas chiefly concentrated on immunoreaction and inflammation response." (PMID 35277559, 2022). "Previous studies have revealed that cathepsin B contributes to glioma invasion by activating uPA and MMPs and suppressing TIMPs." (PMID 35448036, 2022). "We preliminarily profiled the splicing patterns of CTSB for gliomas via TCGA SpliceSeq41, and the exon 8 skip is the most common splicing type of CTSB in gliomas." (PMID 35277559, 2022). "Caffeine reduces mRNA, protein expression, and activity of CTSB via Rho-associated protein kinase (ROCK), which in turn reduces glioma cell invasion and tumor growth in an orthotopic xenograft animal model via the FAK/ERK signaling pathway." (PMID 36552871, 2022). "Our study showed that CTSB is correlated with many immune activities and inflammatory response processes in gliomas, and mainly act as extracellular exosome, lysosome and membrane raft in extracellular space or on cell membrane." (PMID 35277559, 2022). "This study provides a powerful theoretical basis for the design of CTSB-related therapeutics for gliomas." (PMID 35277559, 2022). "This increase is supported by the higher cathepsin B specific activity in both siTRPML1 glioma cell lines, suggesting that it takes part in the activation of caspases leading to apoptotic cell death." (PMID 33954107, 2021). "Release of CTSB is also important for increased invasion and cancer progression in pancreatic ductal adenocarcinoma, glioma and esophageal adenocarcinoma." (PMID 33809973, 2021). "Inhibition of cathepsin B protects the glioma cells from parvovirus oncolysis, highlighting cathepsin B’s importance in the parvovirus infection." (PMID 33557101, 2021). "Then we identified the key factor-CCNB2 which significantly promoted invasion and excessive proliferation of glioma through CCNB2/SASP/Cathepsin B and CCNB2/SASP/PGE2 axis." (PMID 34512164, 2021). "In this study, we identified a key factor CCNB2 and CCNB2/SASP/Cathepsin B & PGE2 axis inducing cell senescence mediated malignant transformation in glioma." (PMID 34512164, 2021). "CCNB2 induced a senescence-associated secretory phenotype (SASP) of glioma cells, and the malignant progression, such as invasion and excessive proliferation was mediated by secreting SASP cytokines, Cathepsin B and PGE2." (PMID 34512164, 2021). "Then we constructed a coculture cell model to measure the impacts of secreted Cathepsin B on migration and invasion of glioma cells." (PMID 34512164, 2021). "CTSB protein expression was found to be associated with GBM cells, macrophages/microglia cells and endothelial cells in glioma tissue sections." (PMID 33312949, 2020). "Downregulation of uPAR and cathepsin B simultaneously caused the downregulation of phospho Akt, phospho p38 (MAPK), and PI3K and inhibit glioma cell migration." (PMID 32764572, 2020). "Elevated expression of cathepsin B and cathepsin D has been observed in many tumor types such as infantile hemangioma, oral tongue squamous cell carcinoma, MG, and gliomas including GB." (PMID 30949483, 2019). "Our data give credence to the previous finding, which demonstrated the prominent expression of CTSL and CTSB in tumor cells as well as in vascular endothelial cells of glioma." (PMID 31824841, 2019). "Malignant transformation results in the overproduction of cathepsin B and elevated cathepsin B levels correlate with increased invasiveness and recurrence of MG, astrocytoma and gliomas." (PMID 30949483, 2019). "Another such substrate is tenascin-C, which was found to be cleaved by cathepsin B, resulting in a pro-angiogenic effect in glioma." (PMID 30897858, 2019).
glioma (continued). "Tumor progression and increased cell invasiveness following cathepsin B release are also characteristic for pancreatic ductal adenocarcinoma, esophageal adenocarcinoma, and glioma, where cathepsins K and X were also found to be involved." (PMID 30897858, 2019). "In agreement with our results from a rat glioma model, where H-1PV infection led to CTSB overexpression, all G1-L3 and G3-L4 patients showed CTSB induction, in contrast to historical negative controls (right)." (PMID 28967558, 2017). "Inhibition of cathepsin B or D activity attenuates extracellular matrix degradation thus reduces migration of glioma cells." (PMID 28106765, 2017). "The cellular mechanism of virus-induced glioma cell killing has been elucidated and is based on active lysosomal cathepsin B translocation and accumulation in the cytosol of H-1PV-infected glioma cells but not normal cells (astrocytes)." (PMID 28553616, 2017). "It has been demonstrated that, in murine models of glioma and meningioma, uPAR and cathepsin B knock-out inhibited angiogenesis by disrupting the JAK/STAT pathway-dependent VEGF expression." (PMID 27896225, 2016). "A strong upregulation of LC3B, p62, LAMP2 and CTSB was detected in perinecrotic areas in glioblastomas suggesting micro-environmental changes as a driver of autophagy induction in gliomas." (PMID 26956048, 2016). "The acid extracellular environment promoted glioma cells to release cathepsin B, which increased the invasion of glioma cells." (PMID 25886458, 2015). "In contrast, in H-1PV-treated gliomas a striking enhancement of CTSB activity was detected, together with an increase in the total amount of tumor-associated enzyme." (PMID 25954743, 2015). "One recent study related to this issue has shown that transcriptional silencing of metalloproteinase 9 in combination with uPAR/cathepsin B affected DSB repair machinery in human glioma in vitro and in vivo." (PMID 24987841, 2014). "Cathepsin B appeared to mediate cell death because either the inhibitor CA074-Me or cathepsin B gene silencing rescued glioma cells from B10 toxicity under hypoxia." (PMID 24743710, 2014). "On the other hand, downregulation of cathepsin B and uPAR more effectively reduces invasion of human glioma cells in vitro and in vivo in an intracranial xenograft model than downregulation of either cathepsin B or uPAR." (PMID 22093547, 2011). "A second clue to cathepsin involvement in tumor cell migration comes from a study of cathepsin B knockdown in glioma cells." (PMID 17488522, 2007). "Inhibition of glioma cell migration with cathepsin B down-regulation correlated with altered cofilin phosphorylation." (PMID 17488522, 2007). "Thus, we performed quantitative real-time PCR (qRT-PCR) analyses, which confirmed that CTSH, CTSO, CTSF, CTSK, CTSS, CTSV and CTSB were significantly downregulated in glioma cells treated with ar-turmerone." (PMID 37768200, 2023). "Interestingly, the downregulation of CTSB was the most significant in glioma cells treated with ar-turmerone." (PMID 37768200, 2023). "In gliomas, both uPAR and CTSB are overexpressed and can degrade the ECM alone or in combination." (PMID 37576397, 2023). "Overall, our results suggested that ar-turmerone suppresses glioma by inhibiting CTSB." (PMID 37768200, 2023). "Cathepsin B was identified as a key target of ar-turmerone in glioma cells." (PMID 37768200, 2023). "Therefore, CTSB can be used for the molecular pathology diagnosis and prognosis evaluation of gliomas as a promising biomarker." (PMID 35277559, 2022). "According to the expression patterns, prognostic significance and the biological processes of CTSB in gliomas, we deem that CTSB-based therapy might be an important strategy to improve the overall prognosis and the therapeutic reactivity of glioma patients." (PMID 35277559, 2022). "Therefore, it is necessary to explore the relationship between CTSB and infiltrating immune cells in gliomas." (PMID 35277559, 2022).
glioma (continued). "This new finding suggests that CTSB in TME may associate with the immunosuppression and progression of gliomas." (PMID 35277559, 2022). "Moreover, previous studies have preliminarily investigated the potential clinical value of CTSB for gliomas in vitro and vivo." (PMID 35277559, 2022). "More importantly, there were few clues about the role of CTSB in glioma-related immune activities, which greatly limits the understanding of the function and mechanism of CTSB in gliomas and restricts the clinical transformation of CTSB-targeted therapy for gliomas." (PMID 35277559, 2022). "The expression level of cathepsin B correlates with the malignancy of glioma tissues." (PMID 35448036, 2022). "Regarding the role and biological processes of CTSB in gliomas, we found that CTSB is mainly related to signal transduction, immune and inflammatory response, regulation of immune response, leukocyte migration, interferon-gamma-mediated signaling pathway, antigen processing and presentation." (PMID 35277559, 2022). "In our study, p-JNK and p-p65 were decreased as FABP6 was reduced, which may inhibit MMP-2 and cathepsin B expression in glioma." (PMID 34685761, 2021). "In the glioma-derived cell line H4, the Aβ2−x levels were likewise decreased in supernatants by treatment with the more specific, but cell-impermeant CatB-inhibitor CA-074, by CA-074 Me treatment, and by CTSB gene deletion." (PMID 33510618, 2020). "Lysosomal cysteine protease cathepsin B is increased six-fold in GB compared to normal brain tissues, which is further confirmed by studies demonstrating increased cathepsin B expression in GB, compared to anaplastic astrocytomas, low-grade gliomas and normal brain tissues." (PMID 31683669, 2019). "Cathepsin B protein expression was found to be associated with GBM cells, macrophages/microglia cells and endothelial cells, confirming our previous studies on its distribution pattern in glioma tissue sections." (PMID 30046941, 2018). "In human glioma cells, H-1PV infection leads to CTSB dysregulation inducing cell death." (PMID 28967558, 2017). "Interestingly, it has been shown that cathepsin B and D play an important role in human glioma progression and invasion." (PMID 28106765, 2017). "In agreement with preclinical data demonstrating cathepsin B induction and cytosolic translocation in H-1PV-infected human glioma cells, the expression of this lysosomal protease was significantly increased in ParvOryx01 patients, when compared with historical recurrent glioblastoma cases." (PMID 29244745, 2017). "While the role of cathepsin D in GBM remains unclear, it has similar proteolytic actions on the extracellular matrix as cathepsin B, and a positive correlation between the expression level of cathepsin D and glioma grade has been observed." (PMID 28611989, 2017). "Overexpression of cathepsin B has been observed in numerous types of cancers, including in gliomas." (PMID 28611989, 2017). "Furthermore, inhibition of uPAR and cathepsin B in glioma stem cells was associated with decreased expression of SOX2 and Bmi1, suggesting that cathepsin B and uPAR have pivotal roles in maintaining the malignant nature of CSCs in gliomas." (PMID 28611989, 2017). "One further report from the same group suggested that inhibition of uPAR together with cathepsin B might be used in radiation therapy to target glioma-initiating cells." (PMID 24987841, 2014). "Furthermore, cathepsin B is overexpressed in gliomas and serves as a strong prognostic marker for primary tumors of the CNS." (PMID 24039814, 2013). "Therefore, targeting Netrin-1– and cathepsin B–dependent pathways may be a new strategy for glioma therapy." (PMID 37398678, 2023). "Therefore, we analyzed the difference of the expression level of CTSB between these glioma types." (PMID 35277559, 2022). "CTSB could specifically and sensitively indicate mesenchymal glioma." (PMID 35277559, 2022).
glioma (continued). "In conclusion, CTSB is closely related to the malignant pathological subtypes, worse prognosis, immune cells infiltration and immunosuppression of gliomas, which make it a promising biomarker and potential target in the diagnosis, treatment and prognostic assessment of gliomas." (PMID 35277559, 2022). "Meanwhile, CTSB may be a specific and sensitive predictor of mesenchymal subtype gliomas." (PMID 35277559, 2022). "Furthermore, CTSB production by activated microglia is associated with glioma, but not normal cell, apoptosis." (PMID 28967558, 2017). "In gliomas, SMOC1, S100A6, CTSB, SPP1, and IGFBP2 serve as a potential therapeutic target in glioma." (PMID 39530009, 2024). "The downregulation of cathepsin B and uPAR also inhibits the MAPK/JNK pathway and impairs the migration ability of glioma cells." (PMID 37398678, 2023). "Silencing cathepsin B and uPAR can inhibit the c-Met pathway and upregulate H2AX, increasing the radiotherapy sensitivity of glioma cells, and the knockdown of cathepsin L has a similar effect." (PMID 37398678, 2023). "We found that CTSB overexpression partially increased CDK2 and CyclinD1 expression in ar-turmerone-treated glioma cells, while it reduced P27 expression." (PMID 37768200, 2023). "Ar-turmerone treatment reduced the expression of CTSB, CDK2 and CyclinD1, but increased the expression of P27 in glioma cells." (PMID 37768200, 2023). "This was also demonstrated in another study, where VEGF receptor inhibitors impaired the cathepsin B/uPA/MMP-2 pathway and inhibited glioma invasion." (PMID 37398678, 2023). "Reducing cytosolic p-JNK by downregulating uPAR and CTSB also induces the translocation of MEKK-1-P-JNK complexes from the cytoplasmic matrix to the nucleus, which can inhibit the migration of glioma cells." (PMID 37576397, 2023). "In a previous study, inhibition of cathepsin B and MMP-9 genes in glioma cells by RNA interference successfully reduced tumor growth and angiogenesis and inhibited tumor cell invasion." (PMID 37398678, 2023). "A study on gliomas found that tivozanib, a pan-inhibitor of VEGF receptor, inhibits cathepsin B/uPA/MMP-2." (PMID 37398678, 2023). "High expression of CTSB also facilitates radioresistance of GBM and paediatric glioma via increasing homology recombination." (PMID 35277559, 2022). "Scratch-wound healing and transwell assays demonstrated that secreted Cathepsin B from CCNB2-related senescent cells obviously facilitated migration and invasion of glioma cells." (PMID 34512164, 2021). "Combined with our studies, Cathepsin B was significantly upregulated in recurrent glioma and HGG, compared to primary glioma and LGG, respectively." (PMID 34512164, 2021). "In conclusion, the correlation of CCNB2/SASP/Cathepsin B & PGE2 axis and senescence mediated malignant transformation in glioma is valuable enough to warrant advanced explorations." (PMID 34512164, 2021). "With clinical information and expression profiles analysis, we found that Cathepsin B and PGE2 synthase-Cox-2 was significantly upregulated in recurrent glioma and HGG, compared to primary glioma and LGG, respectively." (PMID 34512164, 2021). "Downregulation of cathepsin B can induce caspase-8-mediated apoptosis and initiates a partial extrinsic apoptotic cascade in SNB19 human glioma cells." (PMID 31752209, 2019). "Up-regulation of cathepsin B and uPA receptors induces SOX2 and Bmi1 expression, both critical for maintaining the stemness of glioma CSCs, while knockdown of cathepsin B and uPA receptors suppresses expression of SOX2, Bmi1 and nestin, in vivo." (PMID 31683669, 2019). "The expression of cathepsin B has previously been identified in GBM tumor cells, specifically the population of glioma initiating CSCs." (PMID 28611989, 2017). "We then investigated key autophagosomal (LC3B, p62, BAG3, Beclin1) and lysosomal (CTSB, LAMP2) molecules in 350 gliomas using immunohistochemistry, immunofluorescence, immunoblotting and qPCR." (PMID 26956048, 2016).